HAX1 (HCLS1 associated protein X-1)
Description:
Recruits the Arp2/3 complex to the cell cortex and regulates reorganization of the cortical actin cytoskeleton via its interaction with KCNC3 and the Arp2/3 complex. Slows down the rate of inactivation of KCNC3 channels. Promotes GNA13-mediated cell migration. Involved in the clathrin-mediated endocytosis pathway. May be involved in internalization of ABC transporters such as ABCB11. May inhibit CASP9 and CASP3. Promotes cell survival. May regulate intracellular calcium pools.
Synonyms: HAX-1; HS1BP1; HCLSBP1; SCN3
Tractability: Antibody: UniProt places it where antibodies can reach, with high confidence; its Gene Ontology location is reachable by antibodies, with medium confidence. PROTAC: ubiquitination databases record sites on it; its protein half-life has been measured.
Gene: Protein-coding gene on chromosome 1 (154,269,393 to 154,275,882, forward strand). Ensembl gene ENSG00000143575.
Subcellular location: Mitochondrion matrix; Endoplasmic reticulum; Nucleus membrane; Cytoplasmic vesicle; Cytoplasm, cell cortex; Cell membrane; Sarcoplasmic reticulum; Cytoplasm, P-body; Cytoplasm (Isoform 1); Nucleus; Cytoplasm (Isoform 3); Cytoplasm (Isoform 4); Cytoplasm (Isoform 5)
Subcellular location (Human Protein Atlas): Mitochondria
Gene Ontology:
Molecular function: interleukin-1 binding; protein binding; signaling adaptor activity; protein domain specific binding
Biological process: cellular response to cytokine stimulus; granulocyte colony-stimulating factor signaling pathway; mitochondrion organization; negative regulation of apoptotic process; positive regulation of granulocyte differentiation; positive regulation of phosphatidylinositol 3-kinase/protein kinase B signal transduction; positive regulation of transcription by RNA polymerase II; regulation of actin filament organization; regulation of actin filament polymerization; regulation of apoptotic process; regulation of autophagy of mitochondrion; regulation of establishment of protein localization to mitochondrion
Cellular component: cytoplasm; endoplasmic reticulum; mitochondrial intermembrane space; mitochondrial matrix; mitochondrial outer membrane; mitochondrion; nuclear membrane; nucleus; plasma membrane; transcription regulator complex; actin cytoskeleton; apical plasma membrane; clathrin-coated vesicle; cytoplasmic vesicle; lamellipodium; nuclear envelope; sarcoplasmic reticulum; cell cortex; P-body
Genetic constraint (gnomAD): Loss-of-function variants: 20 observed, 25.67 expected, observed/expected ratio (o/e) 0.78, 90% interval 0.55 to 1.13. The upper end of that interval is the gene's LOEUF score, 1.13, which puts it in group 4 of 6, group 1 being the genes least tolerant of losing a copy. Missense variants: 321 observed, 339.09 expected, observed/expected ratio (o/e) 0.95, 90% interval 0.86 to 1.04. Synonymous variants: 108 observed, 119.82 expected, observed/expected ratio (o/e) 0.9, 90% interval 0.77 to 1.06.
Homologues: Orthologues: chimpanzee HAX1 (99% identical), macaque HAX1 (98% identical), guinea pig HAX1 (86% identical), pig HAX1 (84% identical), dog HAX1 (82% identical), mouse Hax1 (81% identical), rat Hax1 (76% identical), tropical clawed frog hax1 (41% identical), zebrafish hax1 (37% identical), Drosophila melanogaster CG4230 (15% identical).
Diseases named in the same sentence as HAX1 in open-access papers:
HAX1 is named in the same sentence as 82 diseases in open-access papers, as found by Europe PMC text mining. Sharing a sentence is not in itself a finding about the gene and the disease. The quoted sentences say what the papers report.
neutropenia (22 papers, 2013 to 2025). A decrease in the number of neutrophils found in the blood. "Mutation of the HAX-1 gene leads to the loss of protein function and the premature apoptosis of neutrophils and nervous cells, thus resulting in neutropenia and neurological dysfunction." (PMID 38811533, 2024). "RNA target identification was performed in the human leukemia cell line HL-60, because promyelocytes represent the most affected cell type in patients with a recessive mutation in both HAX1 alleles (severe neutropenia)." (PMID 36230905, 2022). "Specifically, 2 severe-neutropenia-causing mutants in HAX1 and CLPB, L130 and Y272, respectively, emerge as key regulatory interaction sites enabling protein-protein formation." (PMID 35499078, 2022). "Consistent with its antiapoptotic role in hematopoietic cells, HAX1 deficiency in humans causes severe congenital neutropenia associated also with variable neurological impairment." (PMID 35499078, 2022). "Mutations in HAX1 gene have been described in 36% of patients recorded in the Turkish Severe Congenital Neutropenia Registry." (PMID 32630050, 2020). "When HAX1 is mutated in the region present in all splice variants (usually Q190X), in addition to neutropenia symptoms include neurological abnormalities." (PMID 33146709, 2020). "Rare combinations of ELANE with G6PC3 or HAX1 mutations have been reported, eventually associated with severe neutropenia." (PMID 32630050, 2020). "Beyond ELANE, mutations in the haematopoietic cell-specific Lyn substrate (HCLS) 1-associated gene X1 (HAX1) were identified as a cause of neutropenia." (PMID 25764063, 2015). "Patients with HAX1 mutations present marked neutropenia (absolute neutrophil count < 500 μL−1) which causes life-threatening bacterial infections in newborns." (PMID 25165726, 2014). "With the identification of L130 in HAX1 we thus verify 2 severe-neutropenia-causing mutants in HAX1 and CLPB, L130 and Y272, respectively, as essential residues for complex formation/stability and provide mechanistic evidence explaining a genotype-phenotype correlation." (PMID 35499078, 2022). "On the other hand, mutations inactivating HAX1 result in severe neutropenia (Kostmann disease)." (PMID 33146709, 2020). "Patients with HAX1 deficiency present with marked neutropenia and may have life threatening bacterial infections as early as the newborn period." (PMID 28894446, 2017). "Moreover, it has been known that homozygous mutations in HAX1 gene cause neutrophil apoptosis, resulting in autosomal recessive severe neutropenia in human." (PMID 25275296, 2014). "Interestingly, some studies showed that HAX1 is required to suppress apoptosis in lymphocyte and homozygotic mutations of HAX1 in human caused increased neutrophil apoptosis, resulting in autosomal recessive severe neutropenia." (PMID 25275296, 2014). "Mutations in ELANE, HAX1, GFI1, and SBDS can confirm the diagnosis of SCN, cyclic neutropenia, or SDS." (PMID 40418265, 2025). "HAX-1, as an axiomatic pro-survival protein, was first discovered in congenital severe neutropenia and was shown to inhibit apoptosis in nervous cells." (PMID 38811533, 2024). "Homozygous null mice for HAX1 recapitulate the phenotype of human neutropenia, leading to postnatal lethality." (PMID 25275296, 2014). "Broadly, these conditions can be divided into those where neutropenia is the predominating feature, such as in ELANE, GFI1, HAX1, CSF3R and WAS mutations and those where neutropenia is part of a multi-system disorder." (PMID 23758768, 2013). "Congenital neutropenia is often linked to mutations in genes such as ELANE, HAX1, and SBDS." (PMID 40418265, 2025). "In addition, rare causes of neonatal neutropenia include severe congenital neutropenia due to gene mutations, such as ELANE, HAX1, and G6PC3, as well as neonatal alloimmune neutropenia caused primarily by maternally derived anti-neutrophil antibodies." (PMID 40722810, 2025).
neutropenia (continued). "Since RC-I dysfunction is not the causative mechanism for neutropenia in HAX1-deficient patients, we sought to query a more relevant model system." (PMID 35499078, 2022). "Congenital neutropenias due to mutations in ELANE, SBDS or HAX1 or in the setting of glycogen storage disease (GSD) which is caused by SLC37A4 mutation, often require prolonged granulocyte colony stimulating factor (G-CSF) therapy to prevent recurrent infections and hospital admission." (PMID 31788408, 2019). "It has been suggested that HAX1 is a major inhibitor of apoptosis in myeloid cells and that neutropenia in HAX1-deficient SCN patients is caused by lack of this antiapoptotic function." (PMID 25165726, 2014). "Although the exact role that HAX1 plays in neutrophil ontogeny is unknown; one suggested mechanism is that HAX1 is a major inhibitor of neutrophil apoptosis in myeloid cells and the neutropenia described in HAX1-deficient patients is due to the lack of anti-apoptotic effect." (PMID 28894446, 2017). "In accordance with these findings, HAX-1 (Q190X), a truncated mutant at position 190 leading to neutropenia and neuronal diseases, failed to bind with c-Abl." (PMID 35379774, 2022). "Notably, in patients bearing W44X HAX1 mutation in the region which undergoes alternative splicing, the main transcript variant is non-functional, but the variant in which the mutation is spliced out persists, resulting in neutropenia but without neurological symptoms." (PMID 33146709, 2020). "Therefore, G6PC3 mutation analysis should be considered in all cases of congenital, unexplained neutropenia, regardless of the presence of extra-hematopoietic manifestations or of parental consanguinity, once ELANE and HAX1 mutations are ruled out." (PMID 25391451, 2014).
congenital neutropenia (21 papers, 2009 to 2026). "Biallelic mutations in the human HAX-1 gene lead to autosomal recessive severe congenital neutropenia (SCN or Kostmann syndrome) and neurological abnormalities, mainly resulting from the loss of mitochondrial control of apoptosis." (PMID 35379774, 2022). "Kostmann disease is an autosomal recessive severe congenital neutropenia caused by mutations in HCLS1-associated protein X-1 (HAX1) with aberrant cell death of the myeloid progenitor cells." (PMID 36177048, 2022). "Mutations in the HAX1 gene cause severe congenital neutropenia through mechanisms that are poorly understood." (PMID 36230905, 2022). "With regard to HAX1, patients with mutations in exon 2 encoding isoform A develop isolated congenital neutropenia, whereas other mutations encoding both isoform A and B cause hematological and neurological manifestations (neurological delay, epilepsy)." (PMID 31709206, 2019). "HAX-1, as an axiomatic pro-survival protein, was first reported as a causal mutation in congenital neutropenia (Kostmann disease)." (PMID 29311840, 2017). "Patients with autosomal recessive mutations in the HAX1 gene have a form of severe congenital neutropenia called Kostmann syndrome." (PMID 27335634, 2015). "Homozygous loss-of-function of Hax1 results in severe congenital neutropenia, a life threatening loss of circulating neutrophils in the blood stream." (PMID 27335634, 2015). "Approximately 15% of severe congenital neutropenias (SCNs) are caused by autosomal recessive mutations in the HAX1 gene." (PMID 25165726, 2014). "Recently, it has also been observed that the homozygous mutations in Hax-1 gene or loss of Hax-1 are associated with severe congenital neutropenia and neurodevelopmental disorders." (PMID 25053987, 2014). "Homozygous mutations in the HAX-1 gene are associated with autosomal recessive forms of severe congenital neutropenia along with neurological symptoms." (PMID 22827267, 2012). "Hax1 deficiency causes autosomal recessive severe congenital neutropenia (SCN), or Kostmann disease." (PMID 21217813, 2010). "Kostmann disease is a type of severe congenital neutropenia (SCN) caused by HAX1 deficiency." (PMID 34887872, 2021). "Hax1 is an anti-apoptotic protein with additional roles in cell motility, and autosomal recessive loss of Hax1 results in Kostmann syndrome, a form of severe congenital neutropenia." (PMID 27335634, 2015). "HAX1 deficiency, due to mutations in the HAX1 gene, results in the autosomal recessive severe congenital neutropenia (SCN) called Kostmann disease." (PMID 36230905, 2022). "Loss-of-function mutations of HAX-1 resulted in Kostmann disease, an inherited severe congenital neutropenia syndrome (SCN)." (PMID 35379774, 2022). "The precise pathophysiology of severe congenital neutropenia (SCN) has also remained unclear for a long period of time, despite earlier identification of HAX1 gene mutations as possibly linked to the symptoms." (PMID 34067183, 2021). "HAX-1 mutation or deficiency results in severe congenital neutropenia (SCN), loss of lymphocytes and neurological impairments by largely unknown mechanisms." (PMID 35379774, 2022). "This group includes congenital neutropenia caused by mutations in ELANE, GFI1, HAX1, WAS (X-linked neutropenia), CSF3R, and SRP54 genes." (PMID 31709206, 2019). "Molecular mechanisms underlying congenital neutropenia in patients with HAX1 deficiency are not clear at the moment." (PMID 42086536, 2026). "Similarly, human HAX1 mutations have been associated with autosomal-recessive severe congenital neutropenia (SCN), with hax1 KD in zebrafish embryos resulting in impaired neutrophil development." (PMID 37047441, 2023). "Intrigued by the partial overlap in the clinical manifestation in HAX1 and CLPB deficiency, we hypothesized that HAX1 is functionally downstream of CLPB and that the phenotype of congenital neutropenia in CLPB deficiency is mediated by defective function of HAX1." (PMID 35499078, 2022).
congenital neutropenia (continued). "Antenatal diagnosis has already been performed for the following disorders: severe congenital neutropenia with pathogenic ELANE mutations, Shwachman-Diamond syndrome, WHIM syndrome and glycogen storage disease type Ib and may be offered for many other entities, such as HAX1 and G6PC3." (PMID 21595885, 2011). "In one family, two healthy sons had frequently ANC < 0.5 × 109cells/L and a mild form of congenital neutropenia was exclude with the negative tests for mutation at ELA2 and HAX1 gene locus." (PMID 19323844, 2009).
breast carcinoma (14 papers, 2010 to 2025). "Detailed analysis of expression of five splice variants of HAX1 in breast cancer revealed tumor-specific variations in the pattern of splicing." (PMID 20196840, 2010). "We have also analyzed by semiquantitative and quantitative RT-PCR the expression of five HAX-1 splice variants in breast cancer samples and in normal tissue from the same individuals." (PMID 20196840, 2010). "In MDA-MB-231 breast cancer cell lines resistant to cisplatin or doxorubicin, inhibiting hematopoietic cell-specific protein 1-associated protein X-1 (HAX-1) can induce the release of cyt c from mitochondria, which helps restore the sensitivity of breast cancer cells to chemotherapy drugs." (PMID 41191140, 2025). "Alternatively, HAX1-affinity purification with subsequent mass spectrometry was performed for the two cell lines derived from human cervical carcinoma (HeLa) and breast cancer (MCF7)." (PMID 33146709, 2020). "Based on the IHC data, we assessed the association of the expression of HAX1, KIF14, Mieap, and EZR with breast cancer metastasis." (PMID 32679794, 2020). "To ascertain if HAX1 protein levels in primary tumor can be used as a prognostic factor in breast cancer, we analyzed follow-up patient data and recorded time to distant recurrence and/or time to death from any cause for all 46 patients." (PMID 31093284, 2019). "It was also observed that HAX1 expression differs significantly in molecular subtypes of breast cancer, with the highest expression in basal and luminal B subtypes, associated with more aggressive neoplasm." (PMID 31093284, 2019). "Our previous IHC analysis indicated two different localizations of HAX1 protein in breast cancer tumor samples: cytoplasmic and nuclear." (PMID 31093284, 2019). "Survival analyses of breast cancer patients stratified according to HAX1 expression were performed using KM Plotter and microarray data from 35 breast cancer cohorts from GEO (Gene Expression Omnibus, NCBI)." (PMID 31093284, 2019). "Sheng and Ni reported that higher HAX1 expression was related to a lower 10-year survival rate in breast cancer patients." (PMID 31093284, 2019). "HAX1 is an antiapoptotic factor involved in the regulation of cell migration and calcium homeostasis, overexpressed in several cancers, including breast cancer." (PMID 31093284, 2019). "IHC analysis reported here also reveals its significant overexpression in breast cancer samples from primary tumors, indicating significantly higher HAX1 protein levels in a group of patients who developed distant metastases in a disease course." (PMID 31093284, 2019). "Advancing on our previous study, in which we demonstrated HAX1 overexpression in breast cancer and its differential localization (cytoplasmic and nuclear), we expanded our analysis to assess its effect on metastasis." (PMID 31093284, 2019). "Herein we assessed the potential of HAX1 expression level in primary tumor samples as an independent prognostic factor for breast cancer metastasis." (PMID 31093284, 2019). "HAX1 expression in breast cancer in relation to phenotypic variables was assessed in a set of microarray data using Breast Cancer Gene-Expression Miner v4.1 (bcGenExMiner)." (PMID 31093284, 2019). "In this report we present data analysis which confirms significant HAX1 overexpression in breast cancer samples, coinciding with high amplification of the HAX1 gene." (PMID 31093284, 2019). "Receiver operating characteristic (ROC) analysis was performed to define the best cutoff value of the HAX1 signal and to measure the overall test performance which would use HAX1 protein levels to predict breast cancer metastasis." (PMID 31093284, 2019). "HAX1 overexpression was reported in several cancers, including breast cancer, and its role in metastasis was suggested in some reports." (PMID 31093284, 2019).